LRRK2 (leucine rich repeat kinase 2)
Diseases named in the same sentence as LRRK2 in open-access papers (continued):
Sharing a sentence is not in itself a finding about the gene and the disease.
Parkinson disease (continued). "Leucine-rich repeat kinase 2 (LRRK2) is a highly pursued drug target for Parkinson’s disease (PD), which is the second most common neurodegenerative disease projected to affect 17.5 million people by 20401." (PMID 38263358, 2024). "The existing literature on gender differences in autophagic processes associated with Parkinson’s disease, shown that the main proteins involved are ATG and LRRK2." (PMID 38933683, 2024). "Together, the data reveal distinct differences between WT, VKI, and Haplo mice within the nigrostriatal dopamine system consistent with a LRRK2-dependent gain-of-function in VPS35 p.D620N parkinsonism." (PMID 38110354, 2023). "Mutations in several genes have been associated with monogenic forms of Parkinson's disease, including SNCA, LRRK2, Parkin, PINK1, and DJ-1." (PMID 37841347, 2023). "Our work reveals the structural mechanism of LRRK2 spatial regulation and provides insights into LRRK2 inhibitor design for Parkinson’s disease treatment." (PMID 38127736, 2023). "A major protein degradation pathway, autophagy, is critical to regulating protein turnover in neurons and has been connected to Parkinson’s disease-related mutations including SNCA, LRRK2, VPS35, parkin, Pink1 and DJ-1." (PMID 36864664, 2023). "Since its discovery as the protein responsible for Parkinson’s disease (PD) in the PARK8 locus in 2004, leucine-rich repeat kinase 2 (LRRK2) has been one of the main focus molecules associated with this neurodegenerative disease." (PMID 38002327, 2023). "For example, mutations in the SNCA, LRRK2, and GBA genes have been shown to increase the risk of Parkinson's disease." (PMID 37841347, 2023). "PD-related mutations in LRRK2 and GBA1 slow the degradation of alpha-synuclein, thus directly implicating the dysfunction of the process in the neuropathology of Parkinson’s disease." (PMID 36085537, 2023). "For example, we showed a dichotomy for the LRRK2 interactome expression between the brain and the peripheral tissues; while the brain regions forming the striatum (the structure mostly affected in Parkinson’s) showed a similar functional profile." (PMID 36716346, 2023). "The genes encoding α-synuclein, LRRK2, PRKN, and DJ-1, which regulate microglia activity, play a role as genetic factors in the development of Parkinson’s disease." (PMID 38188026, 2023). "The effect of CGBRE on LRRK2 observed in our study should be assessed on chronic models of UC and Parkinson’s disease." (PMID 38196993, 2023). "Gain-of-function mutations in LRRK2, which encodes the leucine-rich repeat kinase 2 (LRRK2), are the most common genetic cause of late-onset Parkinson’s Disease." (PMID 38127736, 2023). "In the present study, we investigated mitochondrial health and mitophagy under both basal and stress conditions using in vitro LRRK2 models of Parkinson’s disease." (PMID 37384414, 2023). "Inhibition of LRRK2 activity and the resulting improvement of membrane transport and lysosome function is a promising new treatment for Parkinson’s disease." (PMID 37077525, 2023). "Related studies have shown that LRRK2 (Leucine-Rich Repeat Kinase 2) is a potential improvement and therapeutic target for Parkinson’s disease." (PMID 37077525, 2023). "Almost 2 decades after linking LRRK2 to Parkinson’s disease, a vibrant research field has developed around the study of this gene and its protein product." (PMID 37393318, 2023). "The discovery of mutations in LRRK2 and GBA1 that are linked to Parkinson’s disease provided further evidence that autophagy and lysosome pathways are likely implicated in the pathogenic process." (PMID 36085537, 2023). "Leucine-rich repeat kinase 2 (LRRK2), a protein linked to genetic and sporadic Parkinson’s disease (PD), has been revealed as a positive mediator of neuroinflammation, both in in vitro and in vivo studies." (PMID 36830676, 2023).
Parkinson disease (continued). "Leucine-rich repeat kinase 2 (LRRK2) is believed to play an important role in the progression of Parkinson’s disease, with significant efforts underway to identify promising inhibitors to test for therapeutic efficacy." (PMID 36952073, 2023). "Conversely, the kinase hyperactive LRRK2 G2019S Parkinson’s disease mutant suppressed lysosomal degradative activity and gene expression." (PMID 37487100, 2023). "Based on the increased lysosome proteolytic activity following genetic and pharmacological inhibition of LRRK2, we predicted that the gain-of-function LRRK2 G2019S Parkinson’s disease mutant which has increased kinase activity would have the opposite effect." (PMID 37487100, 2023). "Similar results were obtained using the fibroblasts of a LRRK2 G2019S Parkinson’s patient, in which lysosomal morphology defects were corrected with molecular TPC2-silencing or pharmacological inhibition of TPCs." (PMID 36982672, 2023). "The two trait pairs however differed in their strongest association, which was in the SLC2A13 locus on chromosome 12 (shared with LRRK2) for Parkinson’s disease-Crohn’s disease but in the ‘MHC’ locus on chromosome 6 for Parkinson’s disease-UC." (PMID 36687396, 2023). "We will also address the more relevant strategies to modulate neurodegeneration in Parkinson’s disease through the regulation of LRRK2, using small molecules or LRRK2 silencing." (PMID 35743250, 2022). "We found that LRRK2 showed the highest association with microglia and OPCs, and SNCA was the most prominent Parkinson’s disease-associated gene in DaNs." (PMID 34919646, 2022). "Recently, WAVE2 was found to be directly modulated by leucine rich repeat kinase 2 (LRRK2) in microglia, establishing a potentially pathogenic role in development of Parkinson disease." (PMID 35869404, 2022). "LRRK2 in Parkinson is responsible for a much longer tail in the B and E distribution than it is for other PPINs of choice, similarly as in the degree analysis." (PMID 35771625, 2022). "Lovastatin, a β-hydroxy-β-methylglutaryl-coenzyme A (HMG-CoA) reductase inhibitor, activated Akt/Nrf2 pathway and inhibited the downstream gene GSK3β activity and further protected neurite degeneration in LRRK2-G2019S parkinsonism." (PMID 35814229, 2022). "Search terms included “Parkinson’s disease”, “mechanism”, “LRRK2”, and synonyms in various combinations." (PMID 36233046, 2022). "As a key target for Parkinson’s disease, inhibitors for LRRK2 have been developed, but the anticancer effect of this inhibitor has not yet been evaluated." (PMID 36499051, 2022). "From a clinical point of view, mutated LRRK2, corresponding to the PARK8 gene, has been linked to the familial Parkinson’s disease (PD) in an autosomal-dominant manner." (PMID 35897641, 2022). "The 2 major molecular switches in biology, kinases and GTPases, are both contained in the Parkinson disease–related leucine-rich repeat kinase 2 (LRRK2)." (PMID 35192607, 2022). "AMPK, PI3K and PKC are all phosphorylation kinases and Rab35 has been shown to be phosphorylated at Thr72 by LRRK2 in the process of Parkinson’s disease." (PMID 35754325, 2022). "Epitope S1.7 showed mimicry to leucine-rich repeat serine/threonine protein kinase 2 (LRRK2), which is associated with Parkinson’s and inflammatory bowel diseases." (PMID 36207326, 2022). "Pathogenic mutations in the LRRK2 gene increase LRRK2 kinase activity, and LRRK2 kinase inhibitors are neuroprotective in preclinical models of Parkinson's disease." (PMID 35680848, 2022). "Novel LRRK2 inhibitors of the aminoquinazoline structure as potential drugs for the therapy of Parkinson's disease." (PMID 36349142, 2022). "It has been reported that LRRK2 (leucine-rich repeat kinase 2) plays an adaptive role between cancer and Parkinson’s disease and is defined as a new target molecule for cancer therapy due to its increased kinase activity." (PMID 36304266, 2022).
Parkinson disease (continued). "A study shows that RPS15 is a critical morbific leucine-rich repeat kinase 2 (LRRK2) substrate in Parkinson’s disease models of drosophila and human neuron." (PMID 35401659, 2022). "Intraneuronal inclusions in Parkinson’s patients are complex structures that also contain LRRK2 and a large number of LRRK2 interacting proteins such as the chaperones Hsc70 and Hsp73." (PMID 35743250, 2022). "The enzymatic activities of both GBA and LRRK2 are closely linked to their role in the etiology of Parkinson’s, with loss of glucocerebrosidase (GCase) activity due to mutations in GBA1 and a likely gain of kinase activity due to mutations in LRRK2." (PMID 35805938, 2022). "For LRRK2 p.G2019S parkinsonism, genetic variability within DNM3 has been found as an AAO modifier of disease." (PMID 38835901, 2022). "The kinase activity of leucine-rich repeat kinase 2 (LRRK2) has emerged as the primary target for both therapeutic development and biomarker design in Parkinson’s disease (PD)." (PMID 35676398, 2022). "Leucine rich repeat kinase 2 (LRRK2) and SNCA are genetically linked to late-onset Parkinson’s disease (PD)." (PMID 35012605, 2022). "Patients with LRRK2 parkinsonism share clinical features and disease courses which resemble closely to those with idiopathic PD." (PMID 35754954, 2022). "Pharmacological inhibition of LRRK2 using small molecules targeting its kinase activity are entering the clinical evaluation for the treatment of Parkinson's disease, and promising safety data have been reported with the first‐in‐class compound DNL201." (PMID 36051080, 2022). "Our method yields penetrance estimates which align with those obtained via existing approaches in the Parkinson’s disease LRRK2 gene and pulmonary arterial hypertension BMPR2 gene case studies." (PMID 36522764, 2022). "In the context of LRRK2 parkinsonism, genetic and lifestyle penetrance modifiers can help in patient counselling and set the premise for future studies of endogenous protection." (PMID 38835904, 2022). "Addressing evidence from Parkinson’s disease studies, extracellular α-synuclein stimulates leucine rich repeat kinase 2 (LRRK2) expression in monocytes, favoring their infiltration of the brain parenchyma." (PMID 36230921, 2022). "We examine gene-based models, including ones linked to Early-Onset Parkinson’s Disease: PARKIN, PINK1, DJ-1, and SNCA; but we also examine LRRK2, which is linked to Late-Onset Parkinson’s Disease." (PMID 35370740, 2022). "Here, we describe the synthesis of novel C-nor-D-homo bile acid derivatives and the 12-hydroxy-methylated derivative of lagocholic acid and their biological evaluation in fibroblasts from patients with either sporadic or LRRK2 mutant Parkinson’s Disease." (PMID 36671460, 2022). "Intriguingly, APP (4621st → 24th) and LRRK2 (2629th → 25th) that are involved in Alzheimer’s disease and Parkinson’s disease, respectively, were suggested as highly probable candidates by GWAB." (PMID 36291657, 2022). "LRRK1 is related to the familial Parkinsonism gene product Park8 (also known as LRRK2) and belongs to the ROCO family of proteins, which contain a Ras of complex proteins (ROC) GTPase domain and a MAPKKK-like kinase domain." (PMID 36254578, 2022). "The co-occurrence of five variants in the LRRK2 gene (very probably in haplotype) could be an important potential risk factor for the development of parkinsonism, even outside the recently described pedigrees in the researched area where endemic parkinsonism is present." (PMID 35054514, 2022). "Comparative transcriptomic and proteomic analyses between the parental LRRK2 p.G2019S iPSCs and isogenic control cells identified novel candidates involved in LRRK2-parkinsonism pathways." (PMID 34551822, 2021). "Along this pathway, mutations in the genes LRRK2 and UCH-L1 have been correlated with Parkinson’s cases by permanently blocking chaperone-mediated autophagy." (PMID 34502143, 2021).
Parkinson disease (continued). "In LRRK2 parkinsonism, the number of cases with pure substantia nigra degeneration is 33% (24 out of 73), while cases with typical LB pathology only comprise 38% (28 out of 73)." (PMID 33494262, 2021). "Genetic evidence in humans, points towards LRRK1 regulating bone biology and LRRK2 contributing to Parkinson's disease." (PMID 33459343, 2021). "Our first identified family LRRK2 PD case with tremor and parkinsonism was born at the time when Charcot named the disease." (PMID 33584195, 2021). "LRRK2 inhibitors attenuate pro-inflammatory cytokines production in activated microglia in culture, thus reducing brain neuroinflammation in Parkinson's disease." (PMID 35071308, 2021). "An example is the quantification of phosphorylation of Rab10 (pRab10), a bona-fide substrate of LRRK2 kinase activity, in response to the administration of LRRK2-inhibitors under development for Parkinson’s disease." (PMID 33562713, 2021). "LRRK2 overactivity contributes to Parkinson’s disease, whereas our previous analyses of public cancer patient data revealed that decreased LRRK2 expression is associated with lung adenocarcinoma (LUAD)." (PMID 33483550, 2021). "A pathway enrichment analysis identified the top 10 modules (p < 0.05), with “LRRK2 in neurons in Parkinson’s disease” among the candidates." (PMID 33466414, 2021). "In vitro and in vivo models of Parkinson’s disease were established to investigate the effects of the lncRNA XIST/miR-199a-3p/Sp1/LRRK2 axis." (PMID 33494069, 2021). "MSA seems to occur at similar frequencies between LRRK2 parkinsonism and sporadic PD, but LRRK2 cases with PSP are 2.5 times higher than iPD (22% vs. 8%)." (PMID 33494262, 2021). "Much effort has been devoted to the development of selective inhibitors of the LRRK2 as a potential treatment for LRRK2 driven Parkinson's disease." (PMID 34515301, 2021). "In conclusion, it appears that LRRK2 parkinsonism cases with pure nigrostriatal degeneration are six times more frequent compared to iPD (33% vs. 5%), whereas typical LB pathology is reported at half the frequency as iPD (38% vs. 77%)." (PMID 33494262, 2021). "While rare, three pathogenic LRRK2 cases with pathologically proven MSA have been described, which represent about 4% (3 out of 73 LRRK2 cases) of all reported LRRK2 parkinsonism cases." (PMID 33494262, 2021). "Drugs that target LRRK2 in Parkinson’s disease must be able to cross the BBB in order to reach the brain." (PMID 34285770, 2021). "A candidate for spine loss in Parkinson’s disease is CaN (also known as PP2B), whose excessive activation activates the signalling pathways of MEF2 and cofilin as well as leucine-rich repeat kinase 2 (Lrrk2), which results in spine shrinkage and loss." (PMID 34360985, 2021). "Other research has revealed that other components genetically linked to Parkinson's disease including Rab29 and VPS35 also regulate phosphorylation of Rab proteins via LRRK2." (PMID 33459343, 2021). "Thus, it is possible that mutant LRRK2 through its presynaptic actions on α-synuclein localization and glutamatergic synapse activity could cause a degeneration in dopamine terminals in the striatum, ultimately leading to Parkinson’s disease." (PMID 34749824, 2021). "LRRK2-related parkinsonism and idiopathic PD have similar clinical features and response to dopaminergic therapy." (PMID 31802219, 2021). "Research studies on LRRK2 and Parkinson's disease have shown that Rab10 can be effectively phosphorylated by LRRK2, thus proving the direct relationship between this kinase and substrate." (PMID 35071308, 2021). "We demonstrate here that two key molecular players in Parkinson’s disease, α-synuclein and LRRK2, interact mechanistically via specific effects on the actin cytoskeleton." (PMID 34030727, 2021). "Comparative transcriptomic and proteomic analyses between the LRRK2 p.G2019S iPSCs and isogenic control cells were performed to identify novel molecular targets involved in LRRK2-parkinsonism pathways." (PMID 34551822, 2021).
Parkinson disease (continued). "In our LRRK2 case there was also a parallel between start of esophageal symptoms and the clinical manifestation of subclinical parkinsonism." (PMID 33584195, 2021). "Mutations in the leucine-rich repeat kinase 2 gene (LRRK2, PARK8) are the most frequent genetic causes of Parkinson’s disease, reaching up to 40% in some ethnic groups such as Ashkenazi Jewish and North African Arab Berbers." (PMID 33498474, 2021). "Leucine-rich repeat kinase 2 (LRRK2) is considered as a potential target for the treatment of Parkinson's disease." (PMID 35071308, 2021). "In addition, testing whether there is a convergent structural and biochemical impact of the different coding mutations and risk variants in LRRK2 linked to Parkinson's disease is still, 17 years after the first description of mutations in LRRK2, a key priority for the field." (PMID 34328508, 2021). "This cell line can be used alongside its wild‐type control LRRK2 parental RAW 264.7 (ATCC® SC‐6003TM) to investigate Parkinson's disease." (PMID 33742541, 2021). "LRRK2 is involved in many human diseases and is the most important mutant gene in familial and sporadic Parkinson's disease (PD)." (PMID 35071308, 2021). "Leucine-rich repeat kinase 2 (LRRK2) plays a critical role in the pathogenesis of Parkinson's disease (PD)." (PMID 34306319, 2021). "In HEK293 cells expressing Rab71 and in a LRRK2 mutant (a model for Parkinson’s disease), Golgi fragmentation was limited to the TGN with the cis- and medium-Golgi segments remaining intact." (PMID 33477664, 2021). "Peripheral macrophages can also act as mediators to enhance the expression of Parkinson’s Disease (PD) related genes, such as LRRK2, upregulated by pathogen induced endomembrane damage uncovering a link between membrane damage and onset of PD." (PMID 33886609, 2021). "Peripheral macrophages have been reported to act as mediators enhancing the expression of Parkinson’s Disease (PD) related genes, such as LRRK2 or show impairment in phagocytosis of amyloid beta in AD patients with ApoE4/4 genotype." (PMID 33886609, 2021). "Our findings provide a specific mechanistic link between two key molecules in the pathogenesis of Parkinson’s disease, α-synuclein and LRRK2, and suggest potential new approaches for therapy development." (PMID 34030727, 2021). "This cohort study examines the associations of LRRK2 G2019S and GBA variants with longitudinal cognitive and motor decline in Parkinson disease." (PMID 33881531, 2021). "Apart from α-Synuclein accumulation, Parkinson’s pathology can also be attributed to mutations in genes such as PINK1 (PTEN-induced putative kinase 1), DJ-1, PRKN (parkin) and LRRK2 (leucine-rich repeat kinase 2)." (PMID 34830158, 2021). "The results indicated that miR-199a-3p expression was downregulated, whereas that of XIST, Sp1 and LRRK2 were upregulated in Parkinson’s disease." (PMID 33494069, 2021). "Due to these attributes, HEK293 cells have been used to express mutant proteins associated with neurodegenerative disease, such as α-synuclein, LRRK2 and Tau in Parkinson’s and Alzheimer’s disease." (PMID 33926115, 2021). "In summary, the results of the present study showed that lncRNA XIST sponges miR-199a-3p to modulate Sp1 expression and further accelerates Parkinson’s disease progression by targeting LRRK2." (PMID 33494069, 2021). "The resulting LRRK2 PPI network shows the expected links between different Parkinson genes as well as significantly contributed toward an understanding of the cellular functions of the LRRK2 protein." (PMID 32508578, 2020). "We showed that NGS-PrimerPlex can be applied for the multiplex pathogen detection and sequencing exons of the LRRK2 gene in Parkinson’s disease patients." (PMID 33378360, 2020). "We will focus on the latest advances on the role of LRRK2 and Rab in relation to the endolysosomal system, and discuss the possible link to the pathomechanism of Parkinson’s disease." (PMID 32256311, 2020).